ENSG00000277732
Gene: Miscellaneous RNA gene on chromosome 8 (134,598,318 to 134,598,518, forward strand). Ensembl gene ENSG00000277732.
Gene Ontology:
Biological process: negative regulation of gene expression